TIPE2 (TNF alpha induced protein 8 like 2)
Diseases named in the same sentence as TIPE2 in open-access papers (continued):
Sharing a sentence is not in itself a finding about the gene and the disease.
tumor (continued). "We further confirmed by western blotting that IKE-treated TIPE2−/− tumor MDSCs profoundly enhanced the key ferroptosis defense proteins SLC7A11 and GPX4, but immensely lowered the main lipid peroxidation trigger protein ACSL4 when compared to IKE-treated WT tumor MDSCs." (PMID 39851538, 2025). "On the one hand, the overexpression of TIPE2 in tumor cells induced cell death, proving that it might be a tumor suppressor." (PMID 39851538, 2025). "Concerning the recurrence and mortality rate, low rates of recurrence and patient mortality were associated with high TIPE2 immunostaining, which suggests that the presence of TIPE2-positive immunostaining has a good prognostic impact on UC patients protecting against tumor relapses and mortality." (PMID 40060230, 2025). "Notably, increased expression of stress-induced β2-adrenergic receptors and ROS-mediated TNF-α-induced protein 8-like 2 (TIPE2) contributes to their immunosuppressive function, facilitating tumor immune escape and resistance to anti-tumor therapies." (PMID 40149573, 2025). "To investigate the immunological mechanism underlying the anti-tumor therapeutic effect of ferroptosis treatment sensitized by TIPE2-deficient MDSCs, we checked the distribution of immune cells in the tumor tissues of WT and TIPE2−/− LLC tumor-bearing mice with IKE treatment." (PMID 39851538, 2025). "In addition, the maximum reduction in tumor weight and size was observed in IKE-treated TIPE2−/− LLC or B16F10 tumor-bearing mice compared with the other group." (PMID 39851538, 2025). "However, IKE treatment further significantly retarded tumor growth in TIPE2−/− LLC or B16F10 tumor-bearing mice." (PMID 39851538, 2025). "Similarly, RSL3 markedly augmented CD71 level in WT tumor MDSCs, but TIPE2 deletion blocked the RSL3-upregulated CD71 expression of tumor MDSCs." (PMID 39851538, 2025). "Furthermore, NK‐specific Tipe2 deletion not only prevented the exhaustion of tumor‐infiltrating NK cells but also indirectly improved the antitumor CD8+ T cell response by promoting T‐bet/Eomes‐dependent NK cell effector functions." (PMID 36807566, 2023). "Collectively, TIPE2 may act as a tumor suppressor in EOC through PTEN activation and PI3K/Akt signal inactivation, which in turn leads to GSK3β dephosphorylation." (PMID 36801818, 2023). "Additionally, PTEN was found to be upregulated by TIPE2 overexpression, which is an essential tumor-suppressing gene and a prominent negative regulator of PI3K/Akt signaling pathway." (PMID 36801818, 2023). "To confirm the role of Tipe2−/− NK cells in supporting the antitumor function of CD8+ T cells, we adoptively transferred NK cells into MC38 tumor‐bearing mice to determine the role of NK‐expressed TIPE2 in tumor surveillance and its relationship with CD8+ T cells." (PMID 36807566, 2023). "Taken together, our findings suggest that TIPE2 may serve as a predictive factor for tumor progression in EOC." (PMID 36801818, 2023). "Also, deletion of TIPE2 in NK cells significantly inhibits tumor cell growth in vivo and is accompanied by increased levels of tumor-infiltrating NK cells and increased expression of functional molecules." (PMID 36187930, 2022). "Fourth, TIPE2 expression in tumor cells or tumor microenvironment may have different effects on the prognostic outcome of patients." (PMID 35388275, 2022). "And we found that TIPE2 protein was expressed in both the nucleus and cytoplasm of tumor cells." (PMID 35388275, 2022). "TIPE2 has shown its potential as a novel tumor therapeutic target and biomarker in various cancers." (PMID 35388275, 2022). "TIPE2 is encoded by TNFAIP8L2 and has been identified as a potential checkpoint molecule for NK cells maturation and anti-tumor immunity and so targeting TIPE2 may be a potentially novel NK cell-based immunotherapy approach." (PMID 36187930, 2022). "This different expression pattern of TIPE2 in the tumor cells may be related to different clinical features, which need to be further validated." (PMID 35388275, 2022).
tumor (continued). "This body of research shows that TNFAIP8 and TIPE3 may act as oncogenes, while TIPE2 is likely a tumor suppressor gene." (PMID 36118167, 2022). "In agreement with large amounts of previous evidence for the suppressor role of Tipe2 in tumor cells, we demonstrate that the overexpression in CRC cells can inhibit cell growth, upregulates P21 expression and promotes cell cycle arrest in G0/G1 phase, which are considered to be senescent phenotype." (PMID 34702807, 2021). "Moreover, TIPE2 promoted T cell activation to exert an anti-tumor effect possibly through activation of DCs in a TGFβ1 dependent manner." (PMID 34249724, 2021). "Mechanically, TIPE2 may act as a tumor suppressor by inhibiting survivin and regulating caspase 3/7." (PMID 33850476, 2021). "Our previous results showed that TIPE2 played a pivotal role in tumor progression." (PMID 33850476, 2021). "TIPE2, as a crucial regulator in immune responses and homeostasis, involved in both innate and adaptive immune responses, can regulate tumorigenesis not only directly from the inside of tumor cells, but also indirectly via immune cells." (PMID 34249724, 2021). "However, the expression of TIPE2 was markedly decreased in advanced stages with tumor progression compared to that in normal tissues (P<0.001)." (PMID 33850476, 2021). "The expression of TIPE2 was negatively correlated with tumor size in patients." (PMID 34249724, 2021). "TIPE2 expression was negatively associated with tumor size, LNM, and tumor TMN stage in PDAC." (PMID 33850476, 2021). "By in vitro experiments, we demonstrated that TIPE2 may serve as a tumor suppressor by inhibiting proliferation and promoting apoptosis of pancreatic cells." (PMID 33850476, 2021). "Then we found that TIPE2 could decrease the cell percentage of PD-L1+ DCs in tumor-infiltrating lymphocytes." (PMID 34249724, 2021). "TIPE2 is an essential regulator of tumor apoptosis, inflammation and immune homeostasis." (PMID 34249724, 2021). "Recent evidence has revealed that TIPE2 could suppress the migration of tumor cells by promoting the induction of E-cadherin expression and inhibition of N-cadherin and vimentin expression." (PMID 34630074, 2021). "TIPE2 expression on MDSCs is induced by reactive oxygen species (ROS) produced by tumor cells." (PMID 32509781, 2020). "TIPE2 overexpression reduced the growth of xenograft tumours, when compared to the Mock group." (PMID 30637920, 2019). "The discovery of abnormal expression of TIPE2 in tumors suggests that TIPE2 may have the potential of tumor markers and therapeutic targets." (PMID 33817189, 2019). "We revealed that TIPE2 may effectively interdict neoplasm development, which has potential clinical application values for GC targeted therapies." (PMID 30157801, 2018). "The specificity of TIPE2 in predicting tumor progression was lower than 70%." (PMID 30186591, 2018). "Therefore, our data indicated that although TIPE2 expression was up-regulated in PTC tissues, TIPE2 still serves as a tumor suppressor in PTC, which is similar to that in NSCLC." (PMID 30186591, 2018). "Tumor necrosis factor-alpha-induced protein 8-like 2 (TIPE2) is a novel described tumor suppressor." (PMID 30534358, 2018). "All these results suggested that TIPE2 may serve as a potential immunohistochemical marker, and TIPE2 staining in the surgical specimens could be used to evaluate the risks of tumor invasiveness." (PMID 30186591, 2018). "Our previous research found that by inhibiting the activity of Rac1, TIPE2 could suppress the tumorigenesis and development of tumor cells in HCC and NSCLC." (PMID 30534358, 2018). "In the present study, TIPE2 upregulation in PTC tissues was found to be negatively associated with tumor size, capsule infiltration, peripheral infiltration and tumor T stage, which could be used to predict tumor invasiveness." (PMID 30186591, 2018). "Moreover, TIPE2 suppressed tumor invasiveness by inhibiting Rac1, leading to decreased expression of uPA and MMP9." (PMID 30186591, 2018).
tumor (continued). "TIPE2 has been found to be a tumor suppressor in a number of tumors." (PMID 30186591, 2018). "TIPE2 was predominantly expressed in the cytoplasm of the tumor cells." (PMID 30534358, 2018). "It has been demonstrated that TIPE2 may function as a tumor suppressor by inhibiting several classic oncogenic signaling pathways." (PMID 30186591, 2018). "TIPE2 can maintain immune hemostasis and function as a tumor suppressor." (PMID 30217224, 2018). "However, the molecular mechanisms of TIPE2 contributing to cell proliferation and tumor growth are poorly understood in GC." (PMID 30157801, 2018). "The expression of TIPE2 serves as an IHC biomarker for the evaluation of tumor aggressiveness." (PMID 30186591, 2018). "All these results indicated that TIPE2 protein expression was associated with tumor invasiveness in PTC and TIPE2 may be involved in the progression of PTC." (PMID 30186591, 2018). "As it has been demonstrated that TIPE2 expression is negatively correlated with tumor invasiveness." (PMID 30186591, 2018). "Interestingly, it has been demonstrated that TIPE2 also plays a pivotal role in tumorigenesis and tumor development in the recent years." (PMID 30186591, 2018). "Likewise, TIPE2 acted as a tumor suppressor in GIST as well, for it suppressed the proliferation, colony formation, migration and invasion of GIST cells." (PMID 30534358, 2018). "Moreover, ROC analysis indicated that TIPE2 expression had discriminative validity in differentiating tumor tissues and tumor invasiveness." (PMID 30186591, 2018). "Taken together, we hypothesize that TIPE2 expression was up-regulated during the tumorigenesis of PTC, and the expression of TIPE2 decreased accompanied with increased aggressiveness of tumor cells." (PMID 30186591, 2018). "In tumor tissues with high TIPE2 expression, the invasiveness of tumor cells might be suppressed by TIPE2." (PMID 30186591, 2018). "The effect of TIPE2 on angiogenesis, another key step contributing to tumor metastasis, remains unclear till now." (PMID 27556698, 2016). "Upregulation of TIPE2 can inhibit the HCC’s tumor characteristics." (PMID 27696294, 2016). "Therefore, our data indicate that although TIPE2 expression was obviously high in tumor tissues than in adjacent non-tumor lung tissues, TIPE2 still serves as a tumor suppressor in NSCLC, which is supported by the recent two reports." (PMID 27556698, 2016). "By inhibiting Rac1 activity and suppressing the corresponding downstream effects, such as F-actin polymerization and VEGF expression, TIPE2 functions as a tumor suppressor to control the migration, invasion of NSCLC cells and the angiogenesis in tumor microenvironment." (PMID 27556698, 2016). "The mechanism by which TIPE2 inhibits tumor remains complicated, depends on a variety of factors." (PMID 27556698, 2016). "In line with that in normal lung tissue, here we found that TIPE2 expression was also lower in alveolar epithelial cells but markedly higher in bronchial columnar epithelial cells and macrophagocytes in alveolar lumen in adjacent non-tumor lung tissues." (PMID 27556698, 2016). "Moreover, TIPE2 suppressed tumor invasiveness and angiogenesis via inhibiting the activation of Rac1 and subsequently weakening its downstream effects, F-actin polymerization and VEGF expression." (PMID 27556698, 2016). "So we further analyzed the role of TIPE2 expression in tumor cells on angiogenesis." (PMID 27556698, 2016). "We therefore hypothesized that TIPE2 might be employed by cancer-causing pathogens, such as HBV and HCV, to initiate tumorigenesis or promote tumor growth." (PMID 27696294, 2016). "Furthermore, TIPE2 suppressed tumor invasiveness and angiogenesis via inhibiting the activation of Rac1 and subsequently weakening its downstream effects, including F-actin polymerization and VEGF expression." (PMID 27556698, 2016). "TIPE2 is a newly identified regulator of immunity, while emerging evidence indicates that TIPE2 might be also a novel tumor suppressor." (PMID 27696294, 2016).
tumor (continued). "All these results demonstrated that overexpression of TIPE2 could inhibit the subcutaneous tumor growth in vivo obviously." (PMID 25946186, 2015). "Over-expressing TIPE2 promoted apoptosis of H446 cells in vitro and inhibited tumor growth in vivo." (PMID 25946186, 2015). "In addition, in contrast to murine TIPE2 which is easy to be lost in tumor, expression of human TIPE2 is relatively stable in tumor." (PMID 24274578, 2013). "Moreover, the results from IHC and H&E staining showed that tumor in TIPE2 treatment group had obvious TIPE2 expression and revealed higher differentiation compared with those in the Mock group." (PMID 24274578, 2013). "Furthermore, we analyzed the effect of TIPE2 on the metastasis of HCC in the liver orthotopic implantation tumor model." (PMID 24274578, 2013). "In present study, we analyze the relation of loss or reduced expression of TIPE2 in primary HCC tissues with clinicopathological characteristics, investigate the role of TIPE2 in tumor growth, migration and invasion of HCC in vitro and in vivo and further explore its underlining mechanisms." (PMID 24274578, 2013). "TIPE2-deficient MDSCs resisted IKE-induced ferroptosis by up-regulating SLC7A11 and GPX4, and dissolved ferroptosis-induced immunosuppressive function by down-regulating lipid ROS whilst encouraging T cell proliferation and infiltration into tumor tissues to improve ferroptosis therapy." (PMID 39851538, 2025). "Our analysis results concluded that TIPE2 could be considered a tumor suppressor in the initiation and progression of UC and a good indicator for prognosis, which can be used to assess the risk for tumor progression, and as a potential therapeutic target for UC." (PMID 40060230, 2025). "Mechanically, TIPE2 may act as a tumor suppressor by blocking the PI3K/Akt signaling pathway." (PMID 36801818, 2023). "Moreover, our analysis results indicated that TIPE2 could differentiate tumor metastasis and prognosis." (PMID 35388275, 2022). "TIPE-2 is a member of the tumor necrosis factor-α-induced protein 8 family which performs diverse functions, including the negative regulation of innate and adaptive immunity, transcription factor AP-1 and nuclear factor (NF)-κB activation and tumor suppression." (PMID 33568165, 2021). "Therefore, we inferred that TIPE2 might promote T cell activation to exert anti-tumor effect through activating DCs in a TGFβ1 dependent manner." (PMID 34249724, 2021). "As we know, TGFβ1 plays a key role in triggering PI3K/AKT and Raf/MEK/ERK signaling pathways, and we found that TIPE2 overexpression could reduce TGFβ1 secretion from AsPC-1 cells, and similarly decreased the protein level of TGFβ1 in tumor tissues of tumor-bearing mice." (PMID 34249724, 2021). "Moreover, the tumor-infiltrating lymphocytes from tumor-bearing mice were analyzed by flow cytometry, and showed that TIPE2 could promote T cell activation to exert an anti-tumor effect possibly through activation of DCs in a TGFβ1 dependent manner." (PMID 34249724, 2021). "Therefore, we speculated that TIPE2 may play an anti-tumor role through inhibiting TGFβ1 in tumor microenvironment." (PMID 34249724, 2021). "Moreover, TIPE2 serves as a tumor suppressor via inhibiting the activation of Rac1." (PMID 30186591, 2018). "The detailed mechanism of how TIPE2 suppressed tumor aggressiveness remains largely unknown." (PMID 30186591, 2018). "Moreover, by regulating tumor proliferation and invasiveness, forced TIPE2 expression may be considered as a potential therapeutic strategy in controlling the progression of GIST." (PMID 30534358, 2018). "Our previous research demonstrated that by directly binding with Rac1-GTPases, murine TIPE2 dictates the strength of phagocytosis and oxidative burst in innate immunity, while human TIPE2 could inhibit various malignant behaviors of tumor cells and suppress tumor metastasis." (PMID 30186591, 2018). "Moreover, TIPE2 acts as a tumor suppressor by inhibiting Rac1 related signaling." (PMID 30186591, 2018).
tumor (continued). "In the present study, we found that TIPE2 suppresses tumor invasion and angiogenesis in a Rac1 dependent manner and it also serves as a novel biomarker for prediction of tumor metastasis, suggesting forced TIPE2 expression might be a novel strategy for the treatment of NSCLC." (PMID 27556698, 2016). "Rac1-GTPase is known to promote lamellipodia formation at the leading edge of migrating cells, which are involved in cancer metastasis, this may accounts for the phenomenon that TIPE2 expression was decreased markedly in tumor cells that infiltrated into the stroma." (PMID 27556698, 2016). "Our previous researches showed that although stably expression of murine TIPE2 in Ras 3 T3 cell line significantly delayed tumor onset, TIPE2 tumors, once formed, could grow to the same weight as control because of ubiquitin-mediated degradation of TIPE2 protein in tumor cells." (PMID 24274578, 2013). "Finally, TIPE2 could act both as a tumor suppressor and tumor activator." (PMID 39851538, 2025). "TIPE2 deletion greatly decreased the lipid accumulation and uptake level of IKE-treated tumor MDSCs when compared to IKE-treated WT tumor M-MDSCs." (PMID 39851538, 2025). "Mechanistically, TIPE2 has the capacity to bind directly with RAC1, thereby suppressing its activity and, consequently, hindering tumor progression." (PMID 40904408, 2025). "TIPE2 is a member of the TNFAIP8 family; it not only acts as a negative controller of both innate and adaptive immunity but also has a role in tumor initiation, survival, invasion, and spread." (PMID 40060230, 2025). "We further investigated whether TIPE2 regulates ferroptosis susceptibility in the in vivo MDSCs; WT and TIPE2−/− LLC tumor-bearing (TB) mice were treated with IKE to induce ferroptosis in TME, and then the MDSCs extracted from tumor tissues were detected by flow cytometry." (PMID 39851538, 2025). "To investigate the expression profile of TIPE2 in EOC, we initially collected 12 EOC tumor tissues and 14 normal ovarian tissues." (PMID 36801818, 2023). "Similarly, TIPE2 could inhibit tumor growth in vivo, decrease the expression of Ki-67 and N-Cadherin, and increase the expression of Bax by IHC analysis in tumor tissues isolated from tumor-bearing mice." (PMID 34249724, 2021). "Angiogenesis inhibiting factors also include tumor suppressors (e.g., tumor necrosis factor α (TNFα)-induced protein 8 like 2 (TIPE2, TNFAIP8L2))." (PMID 33276489, 2020). "To determine the diagnostic value of TIPE2 expression in PTC, we constructed receiver operator characteristic (ROC) curves and calculated the area under the curve (AUC) to access whether TIPE2 expression was able to differentiate tumor tissues and normal tissues." (PMID 30186591, 2018). "Further analysis also demonstrated that TIPE2 acts as a biomarker for the diagnosis of PTC and evaluation of tumor invasiveness." (PMID 30186591, 2018). "In the present study, we demonstrated that TIPE2 was a promising biomarker to diagnose NSCLC and predict tumor metastasis." (PMID 27556698, 2016). "How to solve the issue, which selectively targeting TIPE2 in MDSCs did not affect its expression in tumor cells, deserves more consideration, and needs more clinical trials to verify it." (PMID 39851538, 2025). "Consistent with previous reports, IKE treatment alone failed to inhibit the tumor growth in both tumor models and TIPE2 deletion alone delayed the tumor progression." (PMID 39851538, 2025). "TIPE2 and CD36 may be novel biomarkers for predicting tumor metastasis and prognosis in patients with bladder UC and hold promise as therapeutic targets." (PMID 40060230, 2025). "Numerous studies indicate that TIPE2 regulates tumorigenesis not just directly from inside tumor cells, but also indirectly through immune cells." (PMID 36801818, 2023).